MUC4 (mucin 4, cell surface associated)
Diseases named in the same sentence as MUC4 in open-access papers (continued):
Sharing a sentence is not in itself a finding about the gene and the disease.
pancreatic cancer (continued). "FBLN2 interacts with MUC4, leading to a breach of the basement membrane (BM), which promotes the invasion of pancreatic cancer." (PMID 34769264, 2021). "A feature of pancreatic cancer (PC) is the frequent overexpression of tyrosine kinase membrane receptor HER2 along with its membrane partner the MUC4 oncomucin in the early stages of the pancreatic carcinogenesis." (PMID 34830899, 2021). "One study of pancreatic cancer determined that miRNA-150 suppresses cell growth and malignant behavior by targeting MUC4." (PMID 33848981, 2021). "Based on this result, we investigated NF-κB p50 implication on miR-210-3p transcriptional regulation under MUC4 control in pancreatic cancer cells." (PMID 34944818, 2021). "Compared to normal tissues, the expression of MUC4 was significantly higher in bladder cancer, cervical cancer, lung cancer, and pancreatic cancer." (PMID 34336844, 2021). "The available evidence indicates that MUC4 is overexpressed in pancreatic cancer and contributes to the aggressiveness and metastasis of pancreatic cancer." (PMID 34336844, 2021). "In this study, we aimed at investigating MUC4-miR-210 roles in earlier stages of pancreatic tumor formation before the hypoxia response activation." (PMID 34944818, 2021). "It is reported that MUC4 induced angiogenesis through nuclear translocation of β-catenin in pancreatic cancer." (PMID 34041244, 2021). "This is probably related to reduced levels of miR-150 expression in pancreatic cancer cells, as an inverse correlation was observed between the amount of MUC4 protein and the level of microRNA-150 expression." (PMID 34680441, 2021). "The recombinant MUC4 domain and predicted immunogenic T cell epitopes can induce cell-mediated and humoral immune responses against MUC4, suggesting its potential to be used as a vaccine candidate for the treatment of pancreatic cancer." (PMID 34884642, 2021). "Several in vitro and in vivo studies demonstrated that MUC4 modulates pancreatic tumor growth, cell proliferation, invasion and apoptosis." (PMID 34944818, 2021). "The HER2 receptor and its MUC4 mucin partner form an oncogenic complex via an extracellular region of MUC4 encompassing three EGF domains that promotes tumor progression of pancreatic cancer (PC) cells." (PMID 34830899, 2021). "MUC4 plays multifaced roles in cell adhesion, migration, proliferation to promote tumorigenesis and metastasis in pancreatic cancer and other epithelial malignancies." (PMID 34887447, 2021). "A previous study showed a high correlation between hypomethylation status and mRNA expression MUC4, and patients with MUC4 hypomethylation correlated with poor prognosis in pancreatic cancer." (PMID 34336844, 2021). "MUC4 has emerged as a specific dysplasia marker expressed in the early dysplastic lesions prior to several malignancies, including incurable pancreatic cancer." (PMID 34604242, 2021). "As MUC4 is a protein involved in tumor migration and metastasis, the negative regulation by CFTR indicates a protective role and a tumor suppressing function by inhibiting MUC4 and hence pancreatic cancer progression." (PMID 33178018, 2020). "MUC4 expression can further be downregulated by microRNA-150 inhibiting growth, clonogenicity, migration and invasion of pancreatic cancer cells." (PMID 32604718, 2020). "Increase of progenitor cells and gemcitabine resistance by MUC4 overexpression has been observed in pancreatic cancer cells." (PMID 33082357, 2020). "In pancreatic cancer, MUC4 is involved in the acquisition of an aggressive phenotype in the early steps of carcinogenesis." (PMID 32206189, 2020). "We also previously observed that down-regulation of MUC4 reversed gemcitabine resistance in pancreatic cancer stem/progenitor cells." (PMID 32098629, 2020). "Expression of MUC1, MUC4, and MUC5AC increases progressively with the advancement of pancreatic cancer, and is associated with poor survival." (PMID 32707920, 2020).
pancreatic cancer (continued). "Here we show interlukine-17 receptor B (IL-17RB) expression is positively correlated with MUC1 and MUC4 expression in pancreatic cancer cells and tumor tissue." (PMID 33082357, 2020). "Together, these results indicate IL17B/IL-17RB signaling is potentially involved in transcriptional regulation of MUC1 and MUC4 expression in pancreatic cancer cells." (PMID 33082357, 2020). "They showed that hypomethylation of MUC1 and MUC4 promoters correlates with mRNA and IHC positivity of both mucins in pancreatic cancer tissues, and with a high CA9 level." (PMID 32707920, 2020). "To evaluate the correlation between IL-17RB, MUC1 and MUC4, we examined the expression of these genes in a panel of human pancreatic cancer cell lines." (PMID 33082357, 2020). "Some researchers assume that mucin 4 (MUC4), a high‐molecular‐weight glycoprotein aberrantly expressed by pancreatic carcinoma cells, helps in the docking of tumour cells on the endothelial surface." (PMID 32886424, 2020). "It has also been reported that TQ inhibits the expression of MUC4 and induces apoptosis in pancreatic cancer." (PMID 31141941, 2019). "Next to that, in vitro and in vivo data in pancreatic cancer show that silencing of MUC4 expression results in altered tumor cell behavior, decreased growth, decreased ErbB2 expression and a marked reduction in metastatic incidence." (PMID 31723153, 2019). "It has been reported that activator protein- (AP-) 2α inhibits MUC4 expression which in turn suppresses proliferation and invasion of pancreatic cancer cells." (PMID 31915505, 2019). "Mucin 4 (MUC4) is a high molecular weight glycoprotein that is differentially overexpressed in pancreatic cancer (PC), functionally contributes to disease progression, and correlates with poor survival." (PMID 31258832, 2019). "Overexpression of MUC4 in triple-negative breast cancer cells induced by RA is an attractive candidate for Src activation because cell knockdown of MUC4 in pancreatic carcinoma decreased Src tyrosine phosphorylation significantly." (PMID 31590252, 2019). "A worse overall survival was observed in MUC4-overexpressing patients with biliary tract carcinoma (HR 2.41), pancreatic cancer (HR 2.01), and colorectal cancer (HR 1.73)." (PMID 30236127, 2018). "MUC4 is one of the most differentially expressed genes in pancreatic cancer that are thought to be potential clinical targets." (PMID 30236127, 2018). "Immunohistochemistry assays utilizing heat-induced epitope retrieval (HIER) were performed to examine MUC4 protein expression in 44 paraffin-embedded tissues of pancreatic cancers and 20 pancreatic cysts." (PMID 34164227, 2018). "The manifestations of these mucins in pancreatic tumor cells indicate that MUC4 can be potential biomarker for pancreatic cancer diagnosis and possibly early detection." (PMID 34164227, 2018). "Overall, we observed that MUC4/MUC16/MUC20 signature harbored an increased hazard ratio compared with MUC4 alone for pancreatic cancer and to a lower extent in bladder cancer, colon cancer, lung squamous cancer and stomach cancer." (PMID 30236127, 2018). "With increasing clinical identification and diagnosis of pancreatic cysts globally and transformation of some cysts into pancreatic cancer, it is important to evaluate if MUC4 is expressed in pancreatic cysts." (PMID 34164227, 2018). "As expected, pancreatic cancer cell lines harbor the highest MUC4 expression (n = 35, z-score = 2.166, p = 0.0006 against theoretical control median = 0)." (PMID 30236127, 2018). "Altogether, this shows that MUC4 high expression is observed in carcinoma and notably in pancreatic cancer." (PMID 30236127, 2018). "Pancreatic cancer presented the most important hazard ratio for MUC4 (HR = 3.94 [CI 1.81–8.61] p = 0.0005756)." (PMID 30236127, 2018).
pancreatic cancer (continued). "SERS measurements showed that sera from patients with pancreatic cancer produced a significantly higher SERS response for MUC4 compared to sera from healthy individuals and from patients with benign diseases." (PMID 30569241, 2018). "MUC4 has been mapped to chromosome 3 in the q29 region, which was cloned from the human tracheobronchial chromosomal DNA library and a human pancreatic tumor cell line." (PMID 28060749, 2017). "Usually, MUC4 is aberrantly expressed in pancreatic cancer, and contributes to the regulation of cellular differentiation, proliferation, metastasis and chemoresistance." (PMID 28881699, 2017). "MUC4 and its membrane partner the oncogenic receptor ErbB2 interact physically in pancreatic cancer cells, and silencing of ErbB2 results in enhanced gemcitabine sensitivity via upregulation of hCNT1 and hCNT3 expression." (PMID 29144412, 2017). "Another study indicated that upexpression of miR-219-1-3p induced a decrease of cell proliferation and migration in pancreatic cancer by negatively regulating expression of the mucin MUC4." (PMID 28298809, 2017). "These distributions were as same as the pancreatic cancer cell line BXPC-3 which is wild-type MUC4 positive-expression as positive control." (PMID 28060749, 2017). "As a high-molecular-weight member of the transmembrane mucin family, MUC4 mucin plays important roles in the carcinogenesis and malignant progression of human pancreatic cancer." (PMID 28060749, 2017). "Pancreatic cancer cells express high levels of MUC1, MUC4 and MUC16 mRNAs that encode membrane-bound mucins." (PMID 28262838, 2017). "These mean that in order to defeat the refractory and drug-resistant pancreatic cancer with MUC4 expression, some pathways can be explored besides repressing MUC4 transcription, as follows: 1) To improve reversed effects of domain-lacking." (PMID 28060749, 2017). "It has been reported that VEGF and MMP-9 expression reduced in the stable MUC4 knockdown pancreatic cancer cell line." (PMID 27287498, 2016). "Recently, the AMOP domain of MUC4 has been demonstrated to play a role in the metastatic spread of pancreatic cancer cells." (PMID 27483328, 2016). "Concerning pancreatic cancer, it has been shown that MUC4 promoter hypomethylation increases with progression of disease from PanIN to frank PDAC." (PMID 27283771, 2016). "Chronic exposure to nicotine or cigarette smoke leads to increased expression of MUC4 in pancreatic cancer through activation of the α7-nAChR/JAK2/STAT3 and the MEK/ERK1/ERK2 signaling cascade." (PMID 26981122, 2016). "Expression of MUC4 also appears to regulate the localization of β-catenin by regulating the levels of E-cadherin within pancreatic cancer cells through activation of Src and FAK." (PMID 27483328, 2016). "First, we aimed to identify the central mechanism through which pan-EGFR inhibitors inhibits MUC4 protein expression in pancreatic cancer cells." (PMID 25686822, 2015). "To uncover the functional role of MUC4 in PDAC NI, we selectively silenced MUC4 expression in Colo-357 and Capan-1 cells, which express higher levels of MUC4 than other pancreatic cancer cell lines." (PMID 26393880, 2015). "We have further validated the oncogenic role of Muc4 in the spontaneously developing pancreatic cancer mouse progression model." (PMID 25686822, 2015). "Previous reports from our lab have shown that MUC4 is required for progression, and metastasis of pancreatic cancer." (PMID 26035354, 2015). "Canertinib treatment resulted in marginal decrease of pFAK in MiaPaCa-1 cells, whereas complete inhibition of pFAK was achieved in MUC4 positive pancreatic cancer cells (CD18/HPAF and Capan-1)." (PMID 25686822, 2015). "Further, we have also observed that the adaptor molecule Grb2 interacts with both HER3 and MUC4 in pancreatic cancer cells, which suggests that HER3/MUC4 association leads to recruitment of Grb2 for HER3/MUC4 mediated downstream signaling pathway." (PMID 26035354, 2015).
pancreatic cancer (continued). "In HER2 low pancreatic cancer cells, HER3 is overexpressed and associates with MUC4 for increased proliferation of pancreatic cancer cells through PI3K/ERK/c-Myc axis." (PMID 26035354, 2015). "To further confirm that MUC4 inhibition was a gene transcriptional effect of canertinib treatment, we adopted RT-PCR approach by isolating RNA from pancreatic cancer cells treated with canertinib and its corresponding vehicle control." (PMID 25686822, 2015). "IFNγ and Retinoic Acid are also known to induce expression of MUC4 in pancreatic cancer and evoke synergistic effects resulting in enhanced induction of target genes." (PMID 26264026, 2015). "Several studies have demonstrated that MUC4 is involved in progression and metastasis of pancreatic cancer (PC)." (PMID 26035354, 2015). "Here, we found that use of canertinib or afatinib resulted in reduction of MUC4 and abrogation of in vitro and in vivo oncogenic functions of MUC4 in pancreatic cancer cells." (PMID 25686822, 2015). "Collectively, our results suggest that both HER2 and HER3 are indispensable for MUC4 mediated pancreatic cancer cell proliferation." (PMID 26035354, 2015). "We and others have shown that MUC4 mucin is aberrantly overexpressed in various cancers including pancreatic cancer." (PMID 25686822, 2015). "In a separate study on multiple pancreatic cancer cell lines, the MUC4 promoter was found to be induced by E2F1 and STAT1 transcription factors, and the association of these factors with the promoter was enhanced in response to nicotine treatment." (PMID 26264026, 2015). "Upon HER2 knockdown, HER3 and MUC4 appear to be overexpressed leading to increased proliferation and tumorigenesis of pancreatic cancer cells." (PMID 26035354, 2015). "Upon HER2 knockdown in pancreatic cancer cell, we observed an elevated expression of HER3 and MUC4 that leads to increased proliferation of pancreatic cancer cells." (PMID 26035354, 2015). "In the present study, for the first time, we have evaluated the role of EGFR family pan-inhibitors canertinib and afatinib in the inhibition of MUC4-mediated invasion, motility and metastasis of pancreatic cancer cells." (PMID 25686822, 2015). "Previous studies have demonstrated that MUC4 is involved in pancreatic cancer cell proliferation and metastasis and it is differentially expressed at different stages of pancreatic cancer." (PMID 26035354, 2015). "Next we sought to elucidate the mechanism behind HER3/MUC4 mediated pancreatic cancer cell hyperproliferation in HER2 knockdown cells." (PMID 26035354, 2015). "On the other hand, we and others have also demonstrated the role of MUC4 in the mediation of gemcitabine resistance in pancreatic cancer." (PMID 25686822, 2015). "Over a period of one decade, we and others have shown that MUC4 is undetectable in normal pancreas, while its expression increases progressively with the advancement of pancreatic cancer." (PMID 25686822, 2015). "Our study also provides a rationale for combined targeting of HER family proteins to abrogate MUC4 mediated oncogenic signaling for improving pancreatic cancer patient survival." (PMID 26035354, 2015). "MUC4 is a type I transmembrane glycoprotein, and its expression has been shown to strongly correlate with the aggressiveness of various cancers including pancreatic cancer." (PMID 26035354, 2015). "We and others have also shown the differential overexpression of MUC4 in human primary pancreatic cancer tissues ranging from 70-90%." (PMID 25686822, 2015). "Our team previously demonstrated that MUC4 induced the nuclear translocation of β-catenin and potentiated cell growth, metastasis and angiogenesis in pancreatic cancer." (PMID 26393880, 2015).
pancreatic cancer (continued). "Among various mucins, MUC4, a high molecular weight membrane bound mucin, is one of the top most differentially overexpressed (4th gene) in pancreatic cancer." (PMID 25686822, 2015). "It has also been shown that canertinib can down regulate MUC4, a molecule that contributes towards pancreatic cancer aggressiveness." (PMID 25686822, 2015). "We observed elevated expression of PI3K, c-MYC and phosphorylation of ERK in HER2 knockdown cells than control cells, suggesting that HER3/MUC4 mediated hyperproliferation of HER2 low pancreatic cancer cells through the PI3K/ERK/c-Myc pathway." (PMID 26035354, 2015). "Through this preclinical study, we provide evidences for the use of irreversible TKIs as a novel approach to reduce tumor burden as well as incidence of metastasis by down regulating MUC4 in advanced pancreatic cancer patients." (PMID 25686822, 2015). "We explored for the first time the novel role of pan-EGFR family inhibitors in reducing the metastatic potential of pancreatic cancer, with major emphasis on MUC4 inhibition using multiple cell lines and an orthotopic mouse model." (PMID 25686822, 2015). "Consistent with our MUC4 protein expression pattern, the level of MUC4 mRNA was observed to decrease in canertinib treated pancreatic cancer cells (CD18/HPAF and Capan-1)." (PMID 25686822, 2015). "MUC1 and MUC4 have been reported to play significant roles in pancreatic cancer growth, proliferation, metastasis and drug resistance." (PMID 26046375, 2015). "Taken together, we provide evidence that supports the effects of MUC4/Y in the malignant progression of pancreatic cancer." (PMID 25367394, 2014). "First, YY1 binds to the promoter of MUC4 and negatively regulates the expression of this well-known pancreatic cancer-related gene." (PMID 24884523, 2014). "These suggest that MUC4/Y relates to the invasion, progression and distant metastases, which also coincides with the results of in vitro and in vivo experiments based on stable MUC4/Y-overexpressing pancreatic cancer cell models." (PMID 25367394, 2014). "YY1 suppresses invasion and metastasis of pancreatic cancer cells by downregulating MMP10 in a MUC4/ErbB2/p38/MEF2C-dependent mechanism." (PMID 24884523, 2014). "Using lentiviral transfection, we constructed and identified pancreatic cancer PANC-1 cell lines that stably overexpressed the MUC4/Y gene." (PMID 25367394, 2014). "MUC4 plays important roles in the carcinogenesis and progression of multiple human cancers, including pancreatic cancer." (PMID 25367394, 2014). "Previous studies showed that MUC4 and ErbB2 interact physically and transduce signals intracellularly, thus promoting the migratory and metastatic potential of pancreatic cancer cells." (PMID 24884523, 2014). "We quantified the correlation between MUC4/Y and MUC4 expression levels in pancreatic cancer tissues with real-time PCR." (PMID 25367394, 2014). "The YY1 high-level overexpression suppresses invasion and metastasis of pancreatic cancer cells by downregulating MMP10 via a MUC4/ErbB2/p38/MEF2C-dependent mechanism." (PMID 24884523, 2014). "We also explored the potential mechanisms underlying the tumor suppression role of YY1 and found that YY1 suppresses invasion and metastasis of pancreatic cancer cells by downregulating MMP10 in a MUC4/ErbB2/p38/MEF2C-dependent mechanism." (PMID 24884523, 2014). "MUC4 stabilizes HER2 on the plasma membrane by inhibiting its internalization in pancreatic cancer, whereas MUC1 induces the internalization of EGFR and directs it to the nucleus for transcriptional upregulation of oncogenic factors." (PMID 25261375, 2014). "Since MUC1, MUC2 and MUC4 are key mucins in pathological diagnosis of pancreatic neoplasms, our goal is to apply DNA methylation analysis of the three mucin genes using pancreatic juice for early diagnosis of these neoplasms." (PMID 24714692, 2014).